TMEM116 (transmembrane protein 116)
Synonyms: FLJ90167
Tractability: Antibody: UniProt predicts a signal peptide or a membrane-spanning region. PROTAC: ubiquitination databases record sites on it.
Gene: Protein-coding gene on chromosome 12 (111,930,181 to 112,013,908, reverse strand). Ensembl gene ENSG00000198270.
Subcellular location: Endoplasmic reticulum membrane (Isoform 1); Endoplasmic reticulum membrane (Isoform 2)
Subcellular location (Human Protein Atlas): Microtubules; Nucleoplasm
Gene Ontology:
Cellular component: endoplasmic reticulum membrane
Genetic constraint (gnomAD): Loss-of-function variants: 33 observed, 40.06 expected, observed/expected ratio (o/e) 0.82, 90% interval 0.62 to 1.1. The upper end of that interval is the gene's LOEUF score, 1.1, which puts it in group 4 of 6, group 1 being the genes least tolerant of losing a copy. Missense variants: 330 observed, 380.8 expected, observed/expected ratio (o/e) 0.87, 90% interval 0.79 to 0.95. Synonymous variants: 121 observed, 141 expected, observed/expected ratio (o/e) 0.86, 90% interval 0.74 to 1.
Homologues: Orthologues: chimpanzee TMEM116 (99% identical), macaque TMEM116 (97% identical), dog TMEM116 (84% identical), pig TMEM116 (83% identical), rabbit TMEM116 (81% identical), guinea pig TMEM116 (76% identical), mouse Tmem116 (70% identical), rat Tmem116 (66% identical), zebrafish tmem116 (41% identical), tropical clawed frog tmem116 (40% identical). Paralogues in human: GPR157 (20% identical).
Diseases named in the same sentence as TMEM116 in open-access papers:
TMEM116 is named in the same sentence as 20 diseases in open-access papers, as found by Europe PMC text mining. Sharing a sentence is not in itself a finding about the gene and the disease. The quoted sentences say what the papers report.
lung carcinoma (5 papers, 2021 to 2025). "Although it remains unclear whether aberrant increase of TMEM116 is the major cause or the consequence of the disease, alteration of TMEM116 might define a predictive biomarker of lung cancer, and help to develop diagnostic tools." (PMID 34789718, 2021). "In this study, we detected that TMEM116 expression is robustly increased in human lung cancer clinical samples and mouse lung cancer models." (PMID 34789718, 2021). "TMEM116 knockdown in A549, and H1299 cells, showed that TMEM116 is required for lung cancer cell growth, motility and invasion." (PMID 34789718, 2021). "Increased level of TMEM116 was observed in human lung cancer cell lines as compared to normal human bronchial epithelial cells." (PMID 34789718, 2021). "In this study, we identify that TMEM116 is activated in human lung cancer clinical samples and mouse lung cancer model." (PMID 34789718, 2021). "To investigate the role of TMEM116 in lung tumorigenesis, we designed sgRNA targeting TMEM116 in human lung carcinoma cell line A549." (PMID 34789718, 2021). "The activity of TMEM116 signaling pathway suggests a potential target to develop new strategy for the diagnosis and treatment of lung cancer." (PMID 34789718, 2021). "In consistent with findings in human lung cancer, TMEM116 was highly expressed in mouse tumor cells which had lost the characteristics of the airway epithelial cells." (PMID 34789718, 2021). "To investigate whether TMEM116 expression was altered in lung cancer, we examined its expression in the clinical samples of two main subtypes of non-small-cell lung cancer (NSCLC), lung adenocarcinoma (LUAD) and lung squamous cell carcinomas (LUSC)." (PMID 34789718, 2021). "Current study is the first to demonstrate the role of TMEM116 in lung oncogenesis and suggest that TMEM116 may be a potential therapeutic target of lung cancer." (PMID 34789718, 2021). "Knockdown TMEM116 also reduced the protein level of PDK1, p-AKT and FOXO3A of lung cancer A549 cells." (PMID 37367036, 2023). "TMEM116 promotes cell migration and invasion, via the regulation of the PDK1-AKT-FOXO3A pathway in lung cancer." (PMID 37367036, 2023). "A growing number of studies revealed that TMEMs were differentially expressed among human cancers, including TMEM116 and TMEM229A in lung cancer, TMEM205 in hepatocellular carcinoma, TMEM168 in glioblastoma, and TMEM180 in colorectal cancer." (PMID 36313638, 2022).
clear cell renal carcinoma (2 papers, 2021). A malignant epithelial neoplasm of the kidney characterized by the presence of lipid-containing clear cells within a vascular network. "Previously the associations between TMEM213 and TMEM30B and between TMEM72 and TMEM116 have been described, however, for clear cell renal cell carcinoma." (PMID 34638224, 2021).
colorectal cancer (2 papers, 2021 to 2022). A primary or metastatic malignant neoplasm that affects the colon or rectum. "And TMEM116, HECTD4, MAPKAPK5 was reported to be associated with renal cell carcinoma, prostate cancer and colorectal cancer." (PMID 35096568, 2021).
atrial fibrillation (1 paper, 2018). A disorder characterized by an electrocardiographic finding of a supraventricular arrhythmia characterized by the replacement of consistent P waves by rapid oscillations or fibrillatory waves that vary in size, shape and timing and are accompanied by an irregular ventricular response. "The TMEM116 gene encodes transmembrane protein 116, which has been reported to be associated with atrial fibrillation and diabetes." (PMID 30096757, 2018).
coronary atherosclerosis (1 paper, 2025). Atherosclerosis of the coronary vasculature. "TMEM116 encoded a transmembrane protein involved in blood coagulation and had been identified as a potential risk gene for coronary atherosclerosis in previous studies." (PMID 41027922, 2025).
melanoma (1 paper, 2021). A malignant, usually aggressive tumor composed of atypical, neoplastic melanocytes. "Our findings would suggest the opposite for TMEM116 in melanoma, and as such it may be like TMEM97, which reportedly has decreased expression in some tumor types and increased expression in others (thus showing both tumor suppressive and oncogenic behaviors in a tissue-dependent context)." (PMID 33963380, 2021).
renal carcinoma (1 paper, 2024). A carcinoma arising from the epithelium of the renal parenchyma or the renal pelvis. "Some proteins of this family are potentially useful for classifying cancer grade in renal cancers (e.g., TMEM45A, TMEM116, TMEM207, TMEM213)." (PMID 38974022, 2024).
cancer (8 papers, 2015 to 2024). A tumor composed of atypical neoplastic, often pleomorphic cells that invade other tissues. "In addition, TMEM116 deficiency inhibited PDK1-AKT-FOXO3A signaling pathway, resulting in accumulation of TAp63, while activation of PDK1 largely reversed the TMEM116 deficiency induced defects in cancer cell motility, migration and invasive." (PMID 34789718, 2021). "Together, these results demonstrate that TMEM116 is a critical integrator of oncogenic signaling in cancer metastasis." (PMID 34789718, 2021). "In current study, we found that BaP-induced cancer cells and clinical tumor samples exhibit increased expression of TMEM116, whereas the epithelial markers are lost." (PMID 34789718, 2021). "Inactivation of TMEM116 reduced cell proliferation, migration and invasiveness of human cancer cells and suppressed A549 induced tumor metastasis in mouse lungs." (PMID 34789718, 2021). "Since the expression of TMEM116 in cancer cells is already much higher than in normal epithelial cells, extra TMEM116 may not make differences." (PMID 34789718, 2021). "Thus, the effects of TMEM116 on cancer cell proliferation, clone formation, migration, and invasion are mainly mediated through PDK1." (PMID 34789718, 2021). "Whether TMEM116 signaling is involved in EMT in later stage of cancer development (malignant cancer cells) needs to be further investigated." (PMID 34789718, 2021). "TMEM116 showed tertiary structure similarity to human B2-adrenergic G protein-coupled receptor (GPCR) and human A2A adenosine receptor, found functionally deregulated in other cancer types and associated with tumor invasiveness and evasion of immune system." (PMID 26169495, 2015). "Therefore, TMEM116 promotes cancer development via the PDK1/AKT/FOXO3A signaling pathway." (PMID 37367036, 2023). "However, little is known about TMEM116 in cancer development." (PMID 34789718, 2021). "In sum, the results of this study demonstrate that TMEM116 via PDK1/AKT/FOXO3A signaling pathway targets TAp63, which is critical in cancer cell motility and tumor metastasis." (PMID 34789718, 2021). "Western blot analysis result confirmed that TMEM116 was highly expressed in human cancer cell lines A549 and H1299, as compared to non-tumor human bronchial epithelial cell line 16HBE." (PMID 34789718, 2021). "However, due to the lack of expression of ΔNp63 in A549 cells, whether TMEM116/PDK1 signaling pathway has effects on ΔNp63 expression in cancer development is query that has not been hitherto addressed." (PMID 34789718, 2021). "In current study, we show that the lack of TMEM116 stimulates TAp63 expression through PDK1 pathway and in turn inhibits cancer cell motility and tumor metastasis." (PMID 34789718, 2021). "Our observation that mesenchymal markers were not detectable in the TMEM116positive cancer cells suggests that TMEM116 may be essential for tumor cell migration/metastasis, but not EMT for primary cancer cells." (PMID 34789718, 2021).
tumor (5 papers, 2015 to 2026). "Univariate Cox regression revealed that, together with other factors, 2-fold increase of TMEM116 expression in tumor tissues is correlated with decreased risk of disease-related mortality (hazard ratio = 0.554, q = 0.086)." (PMID 26169495, 2015). "To further investigate the pathological role of TMEM116 in tumorigenesis and tumor metastasis in vivo, we established xenograft models by injecting stable TMEM116KD A549 cells or control cells (n = 6 per group) into BALB/c nude mice." (PMID 34789718, 2021). "Collectively, these data strongly demonstrate the importance of TMEM116 in tumor metastasis in vivo." (PMID 34789718, 2021). "Whereas, in non-tumor areas TMEM116 was expressed in airway and alveolar epithelial cells." (PMID 34789718, 2021). "To test whether the TMEM116 positive cells underwent epithelial-mesenchymal transition (EMT) in tumor tissues, we conducted immunostaining with antibody against Vimentin and N-Cadherin." (PMID 34789718, 2021). "Targeting TMEM116 by CRISPR-Cas9 in A549 cells significantly reduced cell migration in vitro and tumor metastasis in vivo." (PMID 34789718, 2021). "It revealed that, together with average tumor size, presence of symptoms, and expression of EPAS1, 2-fold increase in the expression of TMEM72 and TMEM116 decreased the odds of metastases significantly for 22 % and 40 %, respectively." (PMID 26169495, 2015). "In clinical samples and benzo(a)pyrene-induced lung cancer mouse models, TMEM116 is expressed in tumor areas lacking airway epithelial or mesenchymal cell characteristics (CC10/β-tubulin and α-SMA)." (PMID 41596760, 2026). "TMEM expression was also dependent on tumor invasion to space surrounding a nerve for ANO1, TMEM116, and TMEM97 (p = 0.002, p < 0.0001, p = 0.008) and on angiolymphatic invasion for TMEM48, RTP3, TMEM173, and TMEM116 (p < 0.0001, p = 0.0267, p = 0.001, p = 0.0053, respectively)." (PMID 34638224, 2021). "In A549 cells, TMEM116 knockdown downregulates PDPK1 (3-phosphoinositide-dependent protein kinase 1; historically referred to as PDK1) and suppresses proliferation, clonogenicity, invasion, and migration in vitro, as well as metastatic burden and subcutaneous tumor growth in vivo." (PMID 41596760, 2026). "Interestingly, TMEM116 positive cells in tumor areas were not labeled by either airway epithelial cell markers (CC10 and β-tubulin) or mesenchymal cell marker (α-SMA)." (PMID 34789718, 2021).
TMEM116 also shares sentences with these, for which no sentence is quoted: breast carcinoma (2 papers); glioblastoma (2); Autoimmunity (1); diabetes (1); hepatocellular carcinoma (1); lung adenocarcinoma (1); lung squamous cell carcinomas (1); non-small cell lung carcinoma (1); prostate carcinoma (1); renal cell carcinoma (1); triple-negative breast carcinoma (1).